CLDN5 (claudin 5)
Diseases named in the same sentence as CLDN5 in open-access papers (continued):
Sharing a sentence is not in itself a finding about the gene and the disease.
schizophrenia (continued). "Taken together, our results indicate that a significant reduction in the expression of CLDN5 protein occurs selectively in the PFC gray matter in patients with schizophrenia, most probably resulting in focal BBB breakdown for small molecules." (PMID 29212157, 2017). "Another study evaluated changes in serum zonulin and CLDN5 levels in schizophrenia patients." (PMID 39940642, 2025). "However, this interpretation is far from settled: one case–control study reported lower serum Cldn5 levels in schizophrenia compared to healthy controls, pointing to temporal or population-specific variability." (PMID 40940757, 2025). "In addition, high levels of IgA antibodies against CLDN5 have been detected in patients with schizophrenia, which is strongly suggestive of paracellular barrier disruption." (PMID 40276385, 2025). "The increased CLDN-5 mRNA level with less translational activity was also induced by pathological stimuli in cultured cells, mouse models of ischemia-reperfusion injury and patients with schizophrenia." (PMID 38898501, 2024). "Recent studies suggest that CLDN-5 expression in the prefrontal cortex of female mice and humans is more easily lowered by social-defeat stress responses via DNA methylation and the prevalence of schizophrenia in individuals with rs10314 is higher in women." (PMID 38898501, 2024). "Further CLDN-5 decline in the hippocampal sub-region in patients with dementia may induce schizophrenia." (PMID 36978081, 2023). "A comprehensive understanding of CLDN-5 based TJs in the ECs and its regulation by pericytes and astrocytes should lead to novel drug targets to treat vascular-mediated dementia, schizophrenia and MDD and to reduce some of the pathologies of other CNS diseases." (PMID 36978081, 2023). "We previously reported that site-selective claudin-5 (CLDN5) breakdown and protein kinase A (PKA) activation are observed in brain microvessels of schizophrenia, but the underlying molecular basis remains unknown." (PMID 33383868, 2020). "Although we have not found direct evidence for transcriptional changes consistent with a leaky BBB in schizophrenia, others report that claudin-5 protein, a tight junction protein, may be reduced in schizophrenia." (PMID 33133060, 2020). "Furthermore, schizophrenia occurs in 30% of individuals with 22q11 deletion syndrome (22q11DS), a population who are haploinsufficient for the claudin-5 gene." (PMID 28993710, 2018). "CLDN5 was observed in the cortical microvessels of both the control and schizophrenic brain tissues, showing that the endothelial-specific distribution is maintained in schizophrenia." (PMID 29212157, 2017). "Thus, cognitive decline may precede the onset of schizophrenia, which is induced by further CLDN-5 decline in the hippocampus by severe hypoperfusion and other stimuli." (PMID 36978081, 2023). "Furthermore, the CLDN5 variant rs10314, which is associated with a decreased claudin-5 expression, was detected in the remaining 22q11.2 region in 9 of 15 22qDS subjects with schizophrenia but in only 8 of 44 22qDS subjects without schizophrenia." (PMID 36676170, 2023). "In addition, this suggests that claudin-5 may be a therapeutic target for schizophrenia, with drugs that regulate its expression representing a more targeted and ultimately safer approach to treatment." (PMID 28993710, 2018). "This does not by any means suggest that variations in claudin-5 is a direct cause of schizophrenia, but that it may be a contributing factor in the development of schizophrenia." (PMID 28993710, 2018). "Thus, expression of CLDN5 mRNA was enhanced in a brain region-specific manner of schizophrenia." (PMID 29212157, 2017). "Additionally, the mRNA and protein levels of CLDN5, claudin-12, and ZO1 were correlated with the age of onset and duration of schizophrenia." (PMID 39940642, 2025).
schizophrenia (continued). "CLDN-5, PUM1 and PUM2 mRNA levels in the post-mortem hippocampal sections of patients with bipolar (BP), schizophrenia (SCZ) and major depressive disorders (MDD) were measured as BBB integrity in the hippocampus is especially vulnerable to oxidative damage and other stress related stimuli." (PMID 38898501, 2024). "A study using post-mortem human brain sections showed that CLDN-5 expression level was attenuated in the grey matter in the hippocampus, but not in the cortex, in the patients with schizophrenia." (PMID 36978081, 2023). "CLDN5 is a major BBB component crucial for angiogenesis and endothelial maintenance that has been reported as increased, decreased or unchanged in schizophrenia." (PMID 35885983, 2022). "Moreover, while the relationship between CLDN5 and BBB permeability is evident, the exact mechanisms by which changes in CLDN5 lead to BBB disruption and how this impacts the overall pathophysiology of schizophrenia require further in-depth investigation." (PMID 39940642, 2025). "For instance, EV-containing Cldn5 were detected in blood under neuroinflammatory conditions, venous blood levels were significantly elevated in patients with OCD compared to healthy controls, and serum levels were found to be decreased in patients with schizophrenia." (PMID 40940757, 2025). "Studies have shown that in the prefrontal cortex (non-visual cortex) of schizophrenia patients, CLDN5 mRNA expression is significantly increased while claudin-5 protein levels are decreased, with no apparent abnormalities in the visual cortex." (PMID 39940642, 2025). "In addition, we show that persistent and targeted suppression of claudin-5 at the BBB in mouse models induces a correlative phenotype of psychosis-like behaviours suggesting a regulation of BBB integrity and dynamism may be therapeutically relevant for the treatment of schizophrenia." (PMID 28993710, 2018). "The smaller volume of the hippocampus and CLDN-5 decline in this region was also observed in patients with MDD, but the volume reduction of CA1, CA3, dentate gyrus and total hippocampus, but not CA2, was less severe compared to patients with schizophrenia." (PMID 36978081, 2023).
Cerebral ischemia (29 papers, 2013 to 2025). Restriction of arterial blood supply to the brain associated with insufficient oxygenation to support the metabolic requirements of the tissue. "An animal study showed that fasudil has a specific effect on neurovascular injury after cerebral ischemia/reperfusion by inhibiting Rho-A protein expression and increasing the expression of growth-associated protein-43 and claudin-5." (PMID 35659272, 2022). "In the present study, we evaluated how EA at GV20 and ST36 changed infarct volumes, neurological deficits, and expression levels of TJ-associated proteins ZO-1, claudin-5, and occludin following cerebral ischemia reperfusion within 7 d in Sprague-Dawley rats." (PMID 25009574, 2014). "Cerebral ischemia similarly decreases the expression levels of TJ proteins such as occludin, ZO-1, Claudin-5, and JAM-A." (PMID 36806348, 2023). "The MCAO in vivo model also showed that cerebral ischemia rapidly induced the degradation of occludin and redistribution of claudin-5 in ischemic cerebral microvasculature." (PMID 35627746, 2022). "L-borneol and DL-borneol increased the expression of CLDN5 in an animal model of permanent cerebral ischemia." (PMID 34017247, 2021). "The disruption of the cerebrovascular claudin-5 has been strongly correlated with the dynamic event of BBB breakdown after cerebral ischemia." (PMID 26545366, 2015). "We show that EA promotes BBB tightness by alleviating the disruption of the TJ-related proteins ZO-1, claudin-5, and occludin during the process of cerebral ischemia reperfusion." (PMID 25009574, 2014). "Overexpression of SIRT1 in BMECs rescued claudin-5, occludin, ZO-1, and VE-cadherin expression, while stabilizing claudin-5/ZO-1 interactions to protect against senescence-induced brain endothelial barrier hyperpermeability, cerebral ischemia, and OGD/R." (PMID 39598406, 2024). "Naringenin also showed a neuroprotective profile in an animal model of brain ischemia, reducing apoptosis, inflammation, oxidative stress and neurological deficits through the modulation of claudin-5, MMP9, Nrf2, nucleotide oligomerization domain-like receptor 2 (NOD2) and NF-κB." (PMID 33383852, 2020). "Blood claudin-5 didn’t change in the early phase of cerebral ischemia while blood MMP-9 appeared to increase only marginally with prolongation of MCAO duration, suggesting the changes of these two molecules do not correlate well with the extent of early ischemic BBB damage." (PMID 28079139, 2017). "EA pretreatment for five days was recently shown to significantly reduce BBB permeability and brain edema, which were correlated with alleviation of the degradation of tight junction proteins occludin and claudin-5 following cerebral ischemia-reperfusion in rats." (PMID 26952102, 2016). "Previous reports prove that downregulation of claudin-5 is closely related to cerebral ischemia." (PMID 25009574, 2014). "Aging, cerebral ischemia, and OGD/R have been shown to reduce the expression of SIRT1, occludin, claudin-5, VE-cadherin, and ZO-1 in BMECs, leading to dysregulated BBB permeability." (PMID 39598406, 2024). "In an acute cerebral ischemia model, the BBB was destroyed after 30 min of ischemia, manifested by the destruction of claudin 5 and accompanied by the activation of cleaved-caspase 3 in brain endothelial cells." (PMID 32038167, 2020). "Immunofluorescence staining revealed increased levels of ZO-1 and claudin-5 following cerebral ischemia in the Weisheng-tang-treated group, suggesting that Weisheng-tang reduces the degree of BBB disruption by increasing the levels of ZO-1 and claudin-5." (PMID 31885791, 2019). "Additionally, minocycline was shown to enhance the levels of TJs proteins, specifically ZO-1, occludin, and claudin-5, and to decrease the BBB permeability in an in vivo cerebral ischemia rat model, a condition that also compromises BBB function." (PMID 36009536, 2022).
Cerebral ischemia (continued). "In addition, the effects of Pimavanserin on the expression level of Claudin 5 and endothelial permeability were both abolished by the knockdown of KLF6, indicating that the protective effect of Pimavanserin in cerebral ischemia injury is mediated by KLF6." (PMID 34605354, 2021). "Further investigation showed that administration of 2-BFI attenuated the disruption of the BBB by preserving the expression of tight junction proteins, especially claudin-5, in endothelial cells after TBI, which is consistent with the observations in a cerebral ischemia model." (PMID 31293382, 2019). "In this study, the expression levels of phosphorylated (p)-Src, VEGFA and claudin-5 were determined to investigate the changes occurring in the levels of these proteins and to determine the benefits of PP2 treatment following cerebral ischemia/reperfusion (I/R)." (PMID 25269821, 2014). "To assess the protective effects of AGNHW on the BBB integrity in the cerebral ischemia–reperfusion injury, we extracted the microvessels in the ipsilateral sides of the ischemic brains and examined the expression of MMP-9, MMP-2, and TJ proteins including ZO-1 and claudin-5." (PMID 31191319, 2019).
ischemia (26 papers, 2014 to 2026). A hypoperfusion of the BLOOD through an organ or tissue caused by a PATHOLOGIC CONSTRICTION or obstruction of its BLOOD VESSELS, or an absence of BLOOD CIRCULATION. "The PCB pretreatment prior to t-PA infusion reduced the loss of occludin and claudin-5 in rats following 2 to 8 hr ischemia." (PMID 29850586, 2018). "Accordingly, ischemia caused a time-dependent loss of occludin and claudin-5 in ischemic tissue after t-PA administration." (PMID 29850586, 2018). "In accordance with other studies, our data showed that protein levels of MMP-2 and MMP-9 were induced in an ischemia time-dependent manner, and this change was accompanied by the loss of TJPs occludin and claudin-5." (PMID 29850586, 2018). "In our study, confocal imaging of the peri-infarct regions of the ipsilateral hemispheres indicated that ischemia caused a loss of the claudin-5 immunoreactivity in the blood vessels and disrupted the appearance of the astrocytic foot processes around the endothelial cells." (PMID 25269821, 2014). "Promotes BBB integrity: In a rat ischemia model, progesterone was found to increase tight junction expression through occludin 1 and claudin 5, and reduced inflammation by downregulating metalloproteinases." (PMID 40884186, 2025). "In conditions such as ischemia and lipopolysaccharide-induced injury, Cav-1 expression increases early, contributing to a decrease in claudin-5 and occludin, resulting in the breakdown of the BBB." (PMID 38922036, 2024). "BBB failure can be characterized by reduced levels of TJPs, such as claudin-5 and occludin, after ischemia." (PMID 36445489, 2023). "On the contrary, enhanced Evans Blue extravasation revealed the damaged blood–brain barrier in the VEGF-LOF on > off, and immunostainings for claudin-5 revealed the ischemia-induced vascular damage in the VEGF-LOF on > off animals." (PMID 35175562, 2022). "Multifluorescence immunostainings for the tight junction protein claudin-5 and occludin (in areas of ischemia-induced vascular damage) revealed decreased surface expression of claudin-5 and occludin in VEGF-LOF." (PMID 35175562, 2022). "The activity of MMP9 and MMP2 can break down the BBB via directly degrading tight junction proteins such as occludin and claudin-5, leading to reversible degradation early after the onset of ischemia and initiating vasogenic edema." (PMID 32221863, 2021). "Mounting evidence indicates that the increased permeability of BBB induced by ischemia generally correlates with the alterations of ZO-1, claudin-5, and occludin." (PMID 32256351, 2020). "Western blotting showed that QKL upregulated ZO-1, claudin-5, VE-Cadherin, and occludin, compared to the Ischemia group." (PMID 32908557, 2020). "As expected, KLF4 expression co-localized with Claudin-5 on the cerebral blood vessels in the ischemic hemisphere at days 2 and 7 post-ischemia." (PMID 32264912, 2020). "Delayed rt-PA treatment enhances the fragmentation of occludin and claudin-5 24 h after middle cerebral artery (MCA) occlusion in rats, and reduces claudin-5 at 24 h or occludin and ZO-1 at 48 h after ischemia in mice." (PMID 26834557, 2016). "The BBB opening that occurs in claudin-5-deficient mice is selective for small molecules (<800 D), whereas the BBB disruption that follows ischemia is more severe and less size-selective." (PMID 25269821, 2014). "As the disruption of the BBB that was induced by ischemia increased, claudin-5 expression decreased." (PMID 25269821, 2014). "Following ischemia, claudin-5 immunostaining decreased, the BBB disruption increased and the extravasation of fibrinogen became more intensive and extensive; at 72 h, the extravasation of fibrinogen was massive." (PMID 25269821, 2014). "In a hypertensive rat model, induced ischemia causes increased MMP-2 secretion and degradation claudin-5 and occludin in endothelial tight junctions, leading to breakdown of the blood-brain barrier." (PMID 25412440, 2014).
ischemia (continued). "Although both groups had similar levels of claudin-5 at 1-day post dMCAO (old vs. young: 0.19±0.03 vs. 0.23±0.02, p=0.32), at 3 days post-ischemia, the old group had a lower level of claudin-5 than the young group (old vs. young: 0.22±0.03 vs. 0.3±0.05, p=0.0096)." (PMID 30705764, 2019). "Additionally, the morphology of TJ components identified by antibodies against occludin and claudin-5 appears to be regularly maintained in regions where FITC-albumin massively leaked into the neuropil 25 h after ischemia." (PMID 26834557, 2016). "The findings of this study reveal a beneficial effect by IVIg on ischemia-induced leukocyte recruitment as well as on endothelial permeability (mediated by tight-junction proteins claudin 5 and occludin), as well as an anti-apoptotic effect on endothelial cells mediated by Bcl-2 and Bcl-XL." (PMID 24991401, 2014). "The activities of COX have a critical role in tight junction dysregulation, and the AhR affects target genes such as COX2; thus, the absence of the AhR could explain the 5-day-post-ischemia increase in claudin 5 associated with BBB recovery." (PMID 41452851, 2025). "In detail, post-translational modification of tight junctions in response to ischemia may activate vascular endothelial growth factor, Rho/ROCK, and cyclic AMP/PKA, causing phosphorylation of tight junction proteins (occludin, claudin-5, and ZO-1) and thus increasing BBB permeability." (PMID 33551950, 2020). "IF staining analysis revealed a significant reduction in the average fluorescence intensity of Claudin-5, Occludin, and ZO1 after ischemia induction compared to the sham group." (PMID 40365318, 2025). "Triple staining for CD31, claudin-5, and Evans Blue revealed reduced vascular permeability and increased claudin-5 coverage in VEGF-GOF compared to VEGF-LOF and control 72 h after ischemia." (PMID 35175562, 2022). "We demonstrate that LPA treatment significantly reduced infarct volume by approximately 60% and attenuated cerebral edema at 48 h post-ischemia; This protection was accompanied by preserved BBB integrity and maintained endothelial claudin-5 expression in the ischemic territory." (PMID 42228231, 2026). "Unlike occludin, claudin-5, and ZO-1, which rapidly decreased early after ischemia, tricellulin remained expressed until 6 h after ischemia before gradually declining." (PMID 36806348, 2023). "Similar findings have been reported in a non-pregnant animal model of ischemia/reperfusion, as tight junction proteins claudin-5 and occludin were found to be unchanged in the brain capillaries of mice subjected to kidney ischemia/reperfusion." (PMID 37569342, 2023). "Accordingly, immunoreactivity of ZO-2 or claudin-5 was significantly reduced in infarct regions compared with non-infarct regions 24 h after ischemia." (PMID 26834557, 2016). "The results suggest that 10 % HS could alleviate cerebral oedema possibly through reducing the ischemia induced BBB permeability as a consequence of inhibiting VEGF–VEGFR2-mediated down-regulation of ZO-1, claudin-5." (PMID 27733124, 2016). "Zo-1 and claudin-5 mRNA expression level was significantly decreased at 6, 12 and 24 h following MCAO (#P < 0.05); however, at 6, 12 and 24 h after 10 % HS treatment, Zo-1 and claudin-5 were increased significantly when compared with the corresponding ischemia group (*P < 0.05)." (PMID 27733124, 2016).